HGF (hepatocyte growth factor)
Diseases named in the same sentence as HGF in open-access papers (continued):
Sharing a sentence is not in itself a finding about the gene and the disease.
cancer (continued). "HGF-related actin rearrangement, which is linked to cancer cell morphogenesis and metastasis, is primarily regulated by small GTPase activity, especially RhoA, Rac1, and Cdc42; however, various types of cancer cells use distinct signaling pathways in response to HGF to activate small GTPase." (PMID 35630066, 2022). "Therefore, the aberrant activation of the HGF/c-Met axis is often associated with invasion, metastasis, disease stage, and shorter survival in multiple human cancer types." (PMID 36012373, 2022). "Hepatocyte growth factor (HGF) and its receptor, Met, play key roles in cell motility, with increased levels of HGF/Met having been associated with cell migration, invasion, and drug resistance in several cancer cells." (PMID 35008958, 2022). "HGF/c-Met elevation has been associated with metastatic progression in many major human cancers." (PMID 36291760, 2022). "The HGF/cMET pathway controls diverse cellular functions, such as proliferation, angiogenesis, and migration, and has been associated with the metastatic progression of several human cancers." (PMID 33738970, 2021). "Moreover, the aberrant expression of MET and its ligand, HGF, is associated with poor prognosis and drug resistance in cancers." (PMID 34761497, 2021). "Three frameshift mutations in cancer genes were lost in the PDX tumors: HGF, SPEN, and PIK3CG." (PMID 33602919, 2021). "HGF/c-Met signaling pathways are uncontrolled in human cancer via overexpression of HGF or c-Met, gene amplification, mutational activation of c-Met, down-regulation of Met-targeted miRNA, binding to other ligands, autocrine signaling, or abnormally high HGF levels." (PMID 32117981, 2020). "Furthermore, they found that HGF triggers increased bFGF secretion, which in turn leads to increased oxidative phosphorylation and HGF secretion in cancer-associated fibroblasts (CAFs)." (PMID 31940827, 2020). "However, another study found that HGF plays a crucial role in HCC proliferation induced by cancer-associated fibroblasts from HCC (H-CAFs) in in vitro and in vivo trials." (PMID 32117981, 2020). "Because higher levels of HGF, or more precisely higher levels of tcHGF and pMET, are considered to be associated with cancer progressions such as drug resistance, the non-invasive detection of tcHGF and pMET is expected to be important for the selection of therapeutic drugs." (PMID 33121208, 2020). "Together with the Kumar study, our study provides evidence that HGF/Met signaling may play an important role in maintaining a central hallmark of cancer, the Warburg effect." (PMID 31940827, 2020). "However, in cancer cells, mutation in c-Met stimulates pathways causing aberrant c-Met/HGF axis activation and resulting in development and progression through migration, invasion, and metabolic reprogramming in cancer." (PMID 32607415, 2020). "Among them, the c-MET/HGF-activated pathway is one of the most studied: its deregulation or constitutive activation is associated with cancer onset and progression, and for this reason, it has been considered as a potential target for therapeutic purpose in several solid cancers." (PMID 33212946, 2020). "Another Korean study showed that hepatocyte growth factor (HGF) from cancer-associated fibroblasts (CAF) could upregulate CK19 expression based on cross-talk between CAF and HCC cells." (PMID 32742454, 2020). "Further complicating the cancer-CS relationships is a recently discovered HGF-associated mechanism by which the cancer cells may induce CS in normal cells that, in turn, form a cancer-promoting microenvironment." (PMID 31085799, 2019). "c-Met and HGF have causal roles in cancer cell survival, growth, angiogenesis and metastasis." (PMID 31885879, 2019). "The overexpression of HGF has been associated with a number of different cancers." (PMID 31805854, 2019).
cancer (continued). "We performed DNA methylation profiling in 5 pairs of NSCLC samples (carcinoma tissues, C, and paracarcinoma tissues, NC) using the Illumina Infinium 450k BeadChip, and there were 10 probes mapped to different regions associated with the HGF gene." (PMID 31602259, 2019). "Ovarian tumor cell-fibroblast interactions cause conversion of normal fibroblasts to cancer-associated fibroblasts (CAFs, distinguished by smooth muscle actin expression) and lead to increased tumor cell adhesion and overexpression of HGF and matrix metalloproteinase (MMP)." (PMID 30261690, 2018). "Cancer-associated fibroblasts also directly promote tumorigenesis through the secretion of inflammatory cytokines and growth factors, such as hepatocyte growth factor (HGF), which is recognized by epithelial MET proto-oncogene receptor tyrosine kinase (c-MET) and promotes proliferation and invasion." (PMID 30131940, 2018). "Besides, the HGF produced by normal ovarian fibroblast are much higher than the cancer-associated fibroblast, suggested normal neighbouring fibroblast in supporting cancer cell progression." (PMID 29455663, 2018). "Amplification of MET expression in some cancers would affect interaction of HGF with proteins in the senescence-associated secretory phenotype, as would the stage of angiogenesis in the growth, carcinogenesis and metastasis of tumors in response to Sema3A signaling." (PMID 29854302, 2018). "Moreover, Met and HGF overexpression have been associated with drug resistance to cancer therapy including against EGFR and Raf." (PMID 30406111, 2018). "Additionally, the HGF/c-Met pathway plays a key role in the onset and progression of human cancers, and pathway activation is associated with a poor prognosis." (PMID 30214428, 2018). "Indeed, high expression levels of pro-HGF are frequently observed in various human cancers, particularly in cancer-associated stromal cells." (PMID 30469509, 2018). "Targeting this mutual c-Met-HGF crosstalk between cancer cells and tumor-associated astrocytes by using the BBB-permeable compound Pterostilbene, a resveratrol analog, diminished the stem-like cell phenotype dependent upon this feed-forward signaling loop both in vitro and in vivo." (PMID 29312881, 2017). "Mutated HGF proteins suppress cMET phosphorylation and cancer cell migration in vitro." (PMID 28336955, 2017). "We have demonstrated that HGF is secreted by cancer-associated human PSCs (hPSCs)." (PMID 29100344, 2017). "HGF and IL-11 are anti-inflammatory cytokines; in addition, IL-11 promotes bone destruction by osteoclasts and inhibits bone formation by osteoblasts, thus causing cancer-induced bone lesions." (PMID 29098000, 2017). "Since it has been reported that cancer-associated mesothelial cells that colonize the peritoneum produce fibronectin, able to trap HGF produced by the fibroblasts of the tumor microenvironment, the inhibition of c-MET activation seems to be a promising target to block cancer metastasis." (PMID 27563880, 2016). "HGF expression level in cancer cells was associated with pathologic differentiation (p=0.001)." (PMID 27374174, 2016). "MET and HGF alterations are indeed associated with clinical outcome, metastasis, invasion and disease severity in human cancers, and identification of patients with specific alterations may be critical to predict clinical response to targeted therapies." (PMID 27013592, 2016). "Here, we show that Ran knockdown results in the reduction of Met, via post-transcriptional regulation, resulting in reduced responsiveness towards HGF-stimulated biological properties associated with cancer progression, and sensitization of cells to gefitinib treatment." (PMID 27716616, 2016). "The dysregulation of HGF/MET pathway has been implicated in many kinds of cancers." (PMID 26254225, 2015). "However, HGF/c-MET axis has also been implicated in the regulation of cancer cell growth, angiogenesis, invasion, and metastasis." (PMID 26137493, 2015).
cancer (continued). "Activation of the HGF/Met axis via MET mutation is frequent in cancer." (PMID 25119536, 2014). "The HGF/MET signaling pathway is associated with cancer cell migration and invasion." (PMID 23829659, 2013). "Further examination on several genes involved in the cancer growth showed that the expressions of hepatocyte growth factor (HGF), fibroblast associated protein (FAP) and alpha smooth muscle actin 2 (ACTA2) were significantly increased in CD90+ subpopulation (p<0.05)." (PMID 24116172, 2013). "Cancer-associated fibroblasts (CAFs) affect tumorigenesis by creating an environment primed for growth and invasion through the secretion of factors, including hepatocyte growth factor (HGF) and transforming growth factor β1 (TGFβ1)." (PMID 24137336, 2013). "HGF and Met have been associated with progression, invasiveness and metastasis in a number of cancer types and for these reasons their signaling is a major target for cancer therapeutics development." (PMID 22745767, 2012). "Our results showed that plasma HGF level was predictive of both all-cause death and cancer death." (PMID 22672958, 2012). "Thus, cancer involves autocrine and paracrine loops, receptor activation and mutation, gene amplification, gene rearrangement, and aberrant HGF activators and inhibitors, presenting a wide array of therapeutic targets." (PMID 17576468, 2007). "Many human cancers exhibit overexpression of HGF and/or c-Met, and several clinical studies revealed that overexpression of HGF and/or c-Met is associated with the prognosis of NSCLC patients." (PMID 15083185, 2004). "HGF/c-Met signaling pathways are deregulated in human cancer by overexpression of HGF or c-Met, gene amplification, mutational activation of c-Met, downregulation of Met-targeted miRNA, binding to other ligands, autocrine signaling or overly high levels of HGF." (PMID 37726886, 2023). "Our study provides arguments for potential alternative use of HGF/c-Met targeted therapies based on their immunomodulatory properties which could lead to the development of new therapeutic associations in cancer patients, for example with immune checkpoint inhibitors." (PMID 34771724, 2021). "Thus, the absence of metastasis in the triple therapy group may be partially due to the loss of cancer cells (secondary to the cytotoxic effect of gemcitabine) and the decreased stemness of the surviving cells due to HGF/c-MET inhibition." (PMID 32203220, 2020). "Thus, it is useful to study whether the level of serum HGF might associate with the synergetic chidamide-crizotinib effect in patients and chidamide could increase the sensitivity of other kinds of cancer cells to crizotinib treatment." (PMID 32792859, 2020). "Interestingly, the activation of the HGF/c-MET axis may be involved in pro-tumoral microenvironment changes caused by cancer cells-released exosomes." (PMID 30642077, 2019). "Therefore, upregulation of SRF may serve as the suppressive mechanism underlying attenuation of HGF seen in LIUS treated non-cancer cells." (PMID 31355136, 2019). "HGF/c-Met mediates cascades that play a key role in tumorigenesis; extensive research on those pathways is not only beneficial for enhancing our understanding of the mechanisms associated with carcinoma, but also suggest promising targets for the development of novel cancer treatments." (PMID 29455668, 2018). "Thus, dysregulation of c-Met and HGF has been implicated in the pathogenesis of cancers." (PMID 29088883, 2017). "However, since HGF has also been implicated in the promotion of migration and angiogenesis, supporting cancer cell survival and metastasis, there is importance in clarifying the expression levels of HGF, its isoforms, and the roles they play, across different tissues." (PMID 28837064, 2017).
cancer (continued). "Cancer associated fibroblasts (CAFs) stimulate malignant cell proliferation by providing different types of growth factors and cytokines in a context-dependent manner, such as HGF, members of the epidermal growth factor family, fibroblast growth factor (FGF), Wnt families, and IL-6." (PMID 26090722, 2015). "These associations may support the role of HGF in many actions of cancer progression." (PMID 25029565, 2014). "Third, the association between HGF and cancer death might be confounded by several factors." (PMID 22672958, 2012). "Here, The effects of TGF-β1, IL-6, and HGF cytokines on the development of TNT conduits between adjacent cancer cells, as well as the effects of oseltamivir phosphate (OP) treatment, were measured using fluorescent microscopy and image analysis software." (PMID 41750361, 2026). "Small interfering RNA (siRNA) technology can be used to affect the interaction between CAFs and cancer cells by reducing the expression of specific target genes such as hepatocyte growth factor (HGF)." (PMID 40038745, 2025). "A recent study showed that PSCs can facilitate the perineural invasion of cancer cells, an alternative route for metastasis, through activation of the HGF/c‐met pathway." (PMID 40437741, 2025). "The treatment with the extracts reduced the cell density in hGF cells, though the effects were less pronounced compared to cancer cell lines, suggesting some selectivity." (PMID 40005959, 2025). "Our study unveils ISR as a pivotal regulator of MET oncogene overexpression in cancer, highlighting a novel layer of translational control that modulates HGF/MET-driven invasive growth." (PMID 39774381, 2025). "Hepatocyte growth factor (HGF) is a multifunctional growth factor known to induce the progression of various cancers through the specific tyrosine kinase receptor MET." (PMID 40299443, 2025). "Further examination and analysis using the annexin-v binding assay and immunoblotting analysis found that cancer cells with MET amplification are more dependent on the HGF/c-MET signaling pathway for oncogenic growth." (PMID 40361420, 2025). "HGF-induced activation of MET signaling axis has been reported to be involved in the progression of various cancers by upregulation of proliferation, invasive activity, motility, and anti-apoptotic activity." (PMID 40076928, 2025). "Enzymatic activity is tightly regulated by HGF activator inhibitor type-1 (HAI-1) and HAI-2 in physiological condition; however, downregulation of HAIs and upregulation of HGF-activating proteases have been reported in various cancers." (PMID 40299447, 2025). "In the context of hepatocellular carcinoma, CAFs boost cancer cell stemness via the ERK1/2-FRA1-HEY1 pathway by secreting hepatocyte growth factor." (PMID 40313969, 2025). "Current studies predominantly rely upon patient-derived xenografts (PDXs) or humanized mouse models that express HGF to study MET-positive cancers and MET-targeting therapeutics." (PMID 39858062, 2025). "In cancer cells, HGF secreted either by cancer cells themselves or by surrounding stromal tissue induces the phosphorylation of c-MET." (PMID 41289612, 2025). "Clinical studies report MET and HGF overexpression correlate with cancer progression and poor prognosis." (PMID 40723207, 2025). "Overall, the c-Met/HGF axis is a central oncogenic driver and is considered an important target in the treatment of cancer." (PMID 40547482, 2025). "This translocation of EGFR from cancer cells to liver cells can inhibit the action of miRNA-26a/b, activate hepatocyte growth factor (HGF), and promote liver metastasis of cancer cells." (PMID 40309240, 2025). "Cancer-associated fibroblasts (CAFs) play a crucial role in promoting treatment resistance in melanoma by directly interacting with cancer cells and releasing soluble mediators such as HGF." (PMID 41013839, 2025).
cancer (continued). "Another study highlighted the role of PSC‐derived hepatocyte growth factor (HGF) in promoting cancer cell invasion and migration via the HGF/c‐Met/survivin pathway." (PMID 40437741, 2025). "This study investigates the EV cargo of human gingival fibroblasts (hGF‐hTERT) following lipopolysaccharide (LPS) stimulation and explores their potential role in cancer progression." (PMID 39967042, 2025). "MET, another attractive RTK target for cancer treatment, is found predominantly in epithelial cells and is activated by its high‐affinity ligand, the hepatocyte growth factor (HGF)." (PMID 39980226, 2025). "Although LsDM showed relatively low cytotoxicity toward hGF cells, its ability to inhibit cancer cell lines was also limited." (PMID 41304951, 2025). "HGF/c-Met signaling has been shown to increase cancer cell invasion and dorsal root ganglia outgrowth in vitro." (PMID 40075699, 2025). "We measured endogenous HGF levels in the conditioned medium of the cancer cells by ELISA at 24 h, 48 h and 72 h after plating the cells, to exclude an effect of endogenous HGF secretion." (PMID 41168417, 2025). "Within the BCBM microenvironment, periostin (POSTN) is produced by POSTN-positive CAFs and promotes cancer cell proliferation by positively regulating the HGF-MET signaling pathway." (PMID 41219968, 2025). "Activation of the HGF/MET signaling axis promotes cancer cell proliferation, anti-apoptosis, motility, invasiveness, and resistance to therapeutic agents." (PMID 40299443, 2025). "These EVs translocate EGFR to the plasma membrane of hepatic stromal cells, subsequently activating HGF/c-Met signaling pathways, thereby supporting cancer cell invasion and liver colonization." (PMID 40149289, 2025). "The results showed a decrease in the c-MET expression, which was mainly observed in regions containing GFP+ cancer cells, and a concurrent increase in HGF expression compared to the control group." (PMID 41289612, 2025). "Cancer cells were treated with 40 ng/ml of HGF, which was manyfold higher than the HGF concentration in the conditioned medium." (PMID 41168417, 2025). "CAFs drive resistance in EGFR-mutant NSCLC by promoting EMT and secreting resistance-inducing factors such as HGF, IL-6, and kynurenine, activating pro-survival pathways in cancer cells." (PMID 40002883, 2025). "The HGF/Met signaling pathway plays a crucial role in promoting cancer cell invasion and metastasis, and it is also involved in the development of drug resistance in certain tumor cells." (PMID 40333783, 2025). "CAFs enhance glycolytic metabolism of cancer cells by secreting paracrine hepatocyte growth factor (HGF)." (PMID 40136652, 2025). "In the study, the authors reported transformation of the cancer cells to facilitate survival, from HGF-independent to HGF-dependent type, under HGF-rich conditions." (PMID 40076928, 2025). "MET is induced by inflammatory stimuli in both mouse and human neutrophils, subsequently activating the endothelium, inducing iNOA production upon HGF stimulation, and promoting cancer cell death." (PMID 40405976, 2025). "HGF is a widely known CAF-secreted factor, and the HGF/MET-axis has often been found to be associated with cancer progression and the induction of therapy resistance." (PMID 40524253, 2025). "The results suggested the significance of HGF-targeted therapy in cancer treatment and overcoming the resistance of MET inhibitor." (PMID 40299447, 2025). "PDGF, CD154 and/or CCL2.73–75 Conversely, fibroblasts and macrophages are important sources of CCL2 and HGF,76,77 which act on cancer cells to increase CCR2 and MET signaling during DCIS progression." (PMID 40736024, 2025). "We attempted to identify hepatocyte growth factor (HGF) inhibitors as novel anti-cancer small-molecule drugs." (PMID 40333783, 2025).